SS18 (SS18 subunit of BAF chromatin remodeling complex)
Diseases named in the same sentence as SS18 in open-access papers (continued):
Sharing a sentence is not in itself a finding about the gene and the disease.
synovial sarcoma (continued). "Immunohistochemical staining in synovial sarcoma patient surgical specimens demonstrated the presence of SS18-SSX and TLE1 as well as the specificity of TLE1 for synovial sarcoma cells." (PMID 27120803, 2016). "The chromosomal translocation t(X;18)(p11.2;q11.2) is the main cytogenetic event in synovial sarcoma and results in the fusion of the BAF complex member SS18 with one of three highly homologous transcriptional repressor genes, SSX1, SSX2 or SSX4." (PMID 27120803, 2016). "In MRT, SMARCB1 is lost due to biallelic inactivation of its gene, whereas in synovial sarcoma, SMARCB1 levels are lowered due to the presence of the SS18-SSX fusion protein." (PMID 27391784, 2016). "In order to visualize SS18-SSX/TLE1 co-localization in synovial sarcoma in situ, we set-up a proximity ligation assay (PLA) using antibodies specifically recognizing SS18 and TLE1." (PMID 27120803, 2016). "When this association is disrupted by specific knockdown of TLE1, ATF2 or SS18-SSX, synovial sarcoma cell lines are observed to undergo apoptosis, indicating this complex association is important for tumor cell survival." (PMID 27120803, 2016). "Nuclear proximity ligation signal is detectable between SS18 and TLE1 in all six tested synovial sarcoma patient derived cell lines: SYO-1 (SS18-SSX2), FUJI (SS18-SSX2), MoJo (SS18-SSX1); Yamato-SS (SS18-SSX1), and ASKA-SS (SS18-SSX1); and CME-1 (SS18-SSX2)." (PMID 27120803, 2016). "Among proteins that colocalize both with SSX and SS18-SSX are PcG proteins, which appear to be an interesting target in synovial sarcoma therapy." (PMID 22550415, 2012). "The presence of the SS18-SSX fusion protein as a result of the t(X:18)(p11.2;q11.2) translocation is a universal feature of synovial sarcoma." (PMID 21197471, 2011). "Several studies have reported the role of SS18‐SSX fusion proteins in activating repressor factors in synovial sarcoma, but there are currently no relevant reports on their involvement in OC." (PMID 39932052, 2025). "Moreover, SS18L1 is a homolog for the SS18 gene and both SS18 and SS18L1 are detected in patients with synovial sarcoma." (PMID 40176070, 2025). "Parker and colleagues supported the role of FYN proto‐oncogene, Src family tyrosine kinase (FYN) in suppressing anti‐cancer activity through SS18‐SSX functional inhibition in order to improve the effectiveness of genetic and histone deacetylase inhibitor (HDACi) treatment against synovial sarcoma." (PMID 40249565, 2025). "FISH assay was conducted to assess the presence or absence of chromosomal rearrangements in the SS18 gene, which is crucial for the diagnosis of synovial sarcoma." (PMID 41149817, 2025). "In this case, disrupting SS18-SSX function may potentiate FYN kinase activation which, in turn, protects synovial sarcoma cell survival." (PMID 40296913, 2025). "To comprehensively interrogate the transcriptomic changes occurring in synovial sarcoma cells upon TAK-981 treatment, we treated HS-SY-II (harboring the SS18::SSX1 fusion) and SYO1 cells (harboring the SS18::SSX2 fusion) with DMSO or TAK-981 and performed bulk RNA sequencing." (PMID 40804185, 2025). "The absence of SS18 gene translocation is a key feature that helps distinguish this tumor from synovial sarcoma." (PMID 40366248, 2025). "Synovial sarcoma is a cancer driven by a fusion oncoprotein, SS18::SSX, that links SS18, a subunit of BAF-family chromatin remodeling complexes, to the carboxy terminus of SSX, which avidly binds nucleosomes with the histone post-translational modification H2AK119ub." (PMID 41423472, 2025). "Our work has identified the proto-oncogene FYN as a direct target of SS18-SSX and shown that suppression of SS18-SSX by a potent HDAC inhibitor (FK228) increases FYN expression levels, which may in turn reduces the treatment response of synovial sarcoma cells." (PMID 39045458, 2024).
synovial sarcoma (continued). "This implies that FYN accumulation, following inhibition of SS18-SSX, could contribute to synovial sarcoma cell survival in a fusion oncogene-independent manner (left)." (PMID 39045458, 2024). "In addition, mutual activation of the nuclear YAP1/TAZ-TEAD and b-catenin-TCF pathways in SS was demonstrated to interact with SS18-SSX, which is crucial for the interdependence of YAP1 and b-catenin in synovial sarcoma." (PMID 39451213, 2024). "In synovial sarcoma samples, there is a chromosome translocation that results in the replacement of C-terminal 8 amino acids of wild type SS18 by 78 amino acids of SSX genes (SSX1, SSX2 or SSX4) to form onco-protein SS18-SSX." (PMID 38678233, 2024). "To examine the clinical relevance of this finding, we analyzed FYN expression in sarcoma patients and found that FYN mRNA levels are significantly lower in synovial sarcoma than in any type of sarcomas that do not carry the SS18-SSX fusion." (PMID 39045458, 2024). "Lack of suitable antibodies detecting endogenous SS18-SSX fusion protein remains a major challenge in studying synovial sarcoma biology." (PMID 39045458, 2024). "The condensates of SS18 recruit BRG1, which can be used as a marker for synovial sarcoma." (PMID 36875159, 2023). "While disruption of normal BAF complex function is central in synovial sarcoma, studies in mice have shown that SMARCB1 loss is not required for SS18-SSX-driven tumorigenesis, generating instead tumors with epithelioid sarcoma features." (PMID 37735617, 2023). "The SS18-SSX fusion oncoprotein has been found to result in genetic transcription changes through alteration in the function of SWI/SNF or BAF complexes, leading to the development of synovial sarcoma." (PMID 36969064, 2023). "Although some genetic features should have a very strong impact on the final diagnosis, such as the finding of an SS18::SSX1 fusion in a suspected synovial sarcoma, they are never sufficient." (PMID 35318454, 2022). "It is interesting to note that the SSX1/2 part of the fusion proteins with SS18 derived from the t(X;18) translocation in synovial sarcoma does not contain the aKRAB of SSX." (PMID 35162997, 2022). "Because synovial sarcoma has a characteristic chromosomal translocation t(X;18) (p11.2; q11.2) in molecular pathology and produces the fusion gene SYT-SSX with corresponding expression of the fusion protein SS18:SSX, it can be detected by FISH and RT–PCR." (PMID 35655305, 2022). "Using the HS-SY-II cell line, which has the SS18::SSX1 fusion gene as a positive control, we show that both ICR-SS-1 and its originating PDX tumour J000104314 harbour the SS18::SSX1 fusion gene, confirming the diagnosis of synovial sarcoma." (PMID 35954262, 2022). "However, a retargeting becomes evident in our data and has also been shown in data published on synovial sarcoma, a cancer entity in which BAF complexes contain an SS18-SSX fusion protein but also lose SMARCB1 in their complexes." (PMID 35456033, 2022). "Synovial sarcoma harbors a t(X;18)(p11;q11) translocation that produces gene fusions between SS18 and SSX1, SSX2 or SSX4, that have not been identified in other neoplasms." (PMID 33921435, 2021). "Synovial sarcoma is a rare, malignant, soft tissue sarcoma that is characterized by the fusion of SS18 with any of several SSX genes, including SS18:SSX1, SS18:SSX2, and SS18:SSX4." (PMID 32204400, 2020). "Similarly, it has been reported that SS18-SSX fusion genes are capable of transforming cells and knockdown of SS18-SSX expression can greatly reduce viability of synovial sarcoma cells, as determined by colony formation assays." (PMID 30416685, 2018). "Next, to test whether SS18-SSX fusions also interact with BRD9 in synovial sarcoma cells, we immunoprecipitated the endogenous fusion protein in two independent synovial sarcoma cell lines." (PMID 30431433, 2018).
synovial sarcoma (continued). "Conventional cytotoxic therapies for synovial sarcoma provide limited benefit, and no drugs specifically targeting its driving SS18-SSX fusion oncoprotein are currently available." (PMID 28056055, 2017). "The SS18-SSX/TLE1/ATF2 protein complex has been shown to be disrupted following treatment with HDAC inhibitors, providing an explanation for the sensitivity of synovial sarcoma cells to HDAC inhibition." (PMID 27120803, 2016). "Given the sensitivity of SMARCB1-deficient tumors to EZH2 inhibition, and the diminution of SMARCB1 levels observed in SS18-SSX translocation positive synovial sarcomas, we hypothesized that synovial sarcomas may be similarly dependent on PRC2/EZH2 activity." (PMID 27391784, 2016). "We investigated the localization pattern of each component of synovial sarcoma-related fusion protein, and examined the inhibiting effect of the localization of SS18-SSX protein in order to understand the mechanisms by which SS18-SSX contributes towards the synovial sarcoma pathogenesis." (PMID 24130893, 2013). "Aside from SS18-SSX, high levels of the transcriptional corepressor named Transducin-like Enhancer of Split 1 (TLE1) is specifically found in most, if not all, of synovial sarcoma tumors and is thereby used as an additional way to indicate the presence of synovial sarcoma in the clinic." (PMID 40296913, 2025). "If so, FYN upregulation may enable synovial sarcoma cells to survive without the need for the presence of SS18-SSX." (PMID 40296913, 2025). "Thus, it seems likely that FYN downregulation in synovial sarcoma is mediated by SS18-SSX regardless of its fusion type." (PMID 39045458, 2024). "Hence, although PCGF3 is essential for synovial sarcoma maintenance, our results indicate that it is not required for SS18-SSX global chromatin binding, suggesting an alternative role for PRC1.3 in this context." (PMID 37735617, 2023). "Therefore, SS18 gene detection was performed to exclude synovial sarcoma; the results were negative, confirming the diagnosis of CS." (PMID 36788533, 2023). "This genetic anomaly unites the transcriptional activating domain of SS18 and the transcriptional repressor domains of SSX, giving birth to a fusion product that is supposed to play an important role in the pathogenesis of Synovial Sarcoma, although the exact mechanism still remains unclear." (PMID 35670050, 2022). "Although the majority of synovial sarcomas do not seem to profit from cancer vaccines targeting the SS18-SSX gene fusion, many other neoantigens derived from gene fusions that drive the oncogenesis in sarcoma types have not yet been included in clinical trials." (PMID 34440251, 2021). "The novel SS18-SSX fusion-specific antibody is reported to have high sensitivity and specificity for the diagnosis of primary synovial sarcoma (SS), which often metastasizes to the lung." (PMID 34127031, 2021). "In addition, the synergy of the SS18-SSX fusion protein and SWI/SNF complex plays an important role in chromatin structure regulation and histone modification, which jointly promote the tumorigenesis and development of synovial sarcoma." (PMID 34381020, 2021). "The chromosomal translocation in synovial sarcoma results in a SS18-SSX fusion protein and it has been demonstrated that circulating CD8+ T cells of HLA-A24+ synovial sarcoma patients can recognise the SS18-SSX peptides and mediate tumour-specific immune responses." (PMID 33207697, 2020). "Therefore, synovial sarcoma is primarily driven not by BAF47 loss, but by the gain of SS18-SSX which seems to be the driving force." (PMID 30898143, 2019). "In the present study, we examined the effects of the cellular context on the function of the synovial sarcoma (SS)-specific fusion protein, SS18-SSX, using human pluripotent stem cells (hPSCs) containing the drug-inducible SS18-SSX gene." (PMID 26571495, 2015).
synovial sarcoma (continued). "SS is characterized by the translocation of ss18 gene on chromosome 18 and synovial sarcoma x (SSX) gene on chromosome X (usually SSX1 or SSX2), which is the driving factor of tumorigenesis and leads to the expression of SS18-SSX fusion protein." (PMID 36003502, 2022). "Importantly, the expression of SS18-SSX is necessary and sufficient for the development of synovial sarcoma, as demonstrated in transgenic mice wherein the conditional expression of SS18-SSX in early myoblasts leads to tumor development without the requirement of any cooperative transgenic changes." (PMID 27120803, 2016). "Interestingly, since co-expression of tSSX2 suppressed cell proliferation and colony formation of the synovial sarcoma SYO-1 and YaFuSS cell lines, the speckle distribution pattern characterized by SS18-SSX might be strongly involved in tumorigenesis of synovial sarcoma cells." (PMID 24130893, 2013). "Using ChIP-Seq, we observed regions where decitabine treatment led to the acquisition of new or increased binding sites for SS18::SSX and KDM2B in HS-SY-II human synovial sarcoma cells that did not correspond to previous KDM2B sites." (PMID 40299558, 2025). "Disruption of Arid1a or Arid1b (both CBAF-specific) retains synovial sarcoma character, while Smarcb1 (PBAF- and CBAF-specific) or Pbrm1 (PBAF-specific) disruption does not, although all accelerate SS18::SSX-driven tumorigenesis in mice." (PMID 41423472, 2025). "None of these analyses identified a SS18-SSX fusion gene, ruling out the possibility that this tumor was a monophasic synovial sarcoma." (PMID 33707600, 2021). "RT-PCR analysis revealed no alternative splice forms of SS18-SSX fusion, which led to the exclusion of synovial sarcoma (data not shown)." (PMID 34333253, 2021). "Synovial sarcomas demonstrate strong and diffuse nuclear expression of TLE1 and SS18-SSX and are negative for CD34 and STAT6." (PMID 32867125, 2020). "The absence of myogenic markers helped to exclude alveolar rhabdomyosarcoma, while ‘next‐generation immunohistochemistry’, which exploits the molecular genetics of mesenchymal neoplasms, including SS18‐SSX and DUX4, helped to rule out synovial sarcoma and CIC‐rearranged sarcomas, respectively." (PMID 40640075, 2025). "Given the ability of SS18-SSX to negatively regulate FYN expression, it would not be surprising, if FYN activation in response to SS18-SSX-targeted therapy served as a poor prognostic factor for synovial sarcoma." (PMID 40296913, 2025). "However, immunostaining for SSX and the SS18-SSX fusion gene, typically positive in synovial sarcoma, was negative in this case, allowing us to rule out this diagnosis." (PMID 39552978, 2024). "However, an important point differentiating synovial sarcoma from MM is negative WT1, with a t(X; 18) or SS18-SSX gene fusion." (PMID 38938650, 2024). "This clinical outcome highlights the need for an improved understanding of the SS18-SSX function in synovial sarcoma biology and raises an interesting possibility that SS18-SSX induces synovial sarcoma development but is not indispensable for synovial sarcoma cell survival." (PMID 40296913, 2025). "Studies have established that, although SS18-SSX is sufficient to drive synovial sarcomagenesis in mice, these models of tumors did not reflect the full biological potential of SS." (PMID 31416195, 2019).
sarcoma (22 papers, 2010 to 2026). A usually aggressive malignant neoplasm of the soft tissue or bone. "Examples of antibodies serving as surrogate markers of sarcoma-specific genetic aberrations, e.g., fusions, amplifications, and point mutations, include SS18-SSX or SSX, TFE3, SMARCB1, BCOR, MDM2, DDIT3, and PAX3." (PMID 40526340, 2025). "The vast majority of this type of sarcoma (> 95%) has an SS18-SSX fusion gene, which serves as a clinical diagnostic marker, as in the presented case." (PMID 39007017, 2024). "SS is considered as a translocation-associated sarcoma because SS18::SSX fusion has been observed in more than 90% of cases." (PMID 38786310, 2024). "Synovial sarcoma is a well-established translocation-associated sarcoma and is defined by the presence of the t (X;18) (p11.2; q11.2) translocation, involving the SS18 (formerly SYT) gene on chromosome 18 and one of several synovial sarcoma X (SSX) genes on chromosome X (usually SSX1 or SSX2)." (PMID 30909651, 2019). "SS18::POU5F1-fused sarcoma is an exceedingly rare malignant tumor, with only isolated case reports documented to date." (PMID 41971444, 2026). "This sarcoma is characterized by the SS18-SSX fusion gene, which plays a pivotal role in epigenetic regulation." (PMID 38539460, 2024). "Similar to the aberrant fusion proteins that drive the development of other human sarcomas, SS18-SSX lacks an enzymatic domain amenable to direct pharmacological targeting." (PMID 33361335, 2021). "Included in the present study were sarcomas being correctly classified with fusion genes such as PAX7-FOXO1, EWSR1-NR4A3, FUS-CREB3L2, and SS18-SSX." (PMID 23967081, 2013). "To uncouple SSX-C specificity from SS18-SSX-mediated BAF complex deregulation, we compared SSX-C binding patterns in HS-SY-II sarcoma cells in the presence or absence of SS18-SSX via inducible short hairpin RNA (shRNA) knockdown." (PMID 37735617, 2023). "The SS18-SSX fusions do not seem to occur in other types of sarcomas." (PMID 21092139, 2010).
Ewing sarcoma (9 papers, 2018 to 2025). A small round cell tumor that lacks morphologic, immunohistochemical, and electron microscopic evidence of neuroectodermal differentiation. "Therefore, based on these functional backgrounds, silencing of co-activator SS18/SSX picked up small amounts of regulated proteins compared to Ewing sarcoma and alveolar rhabdomyosarcoma having either EWS/FLI1 or PAX3/FOXO1 which act as transcriptional factors." (PMID 30680066, 2018).
soft tissue sarcoma (7 papers, 2016 to 2026). A malignant neoplasm arising from muscle tissue, adipose tissue, blood vessels, fibrous tissue, or other supportive tissues excluding the bones. "As previously reported, the Fuji cell line contains an SS18-SSX2 translocation, while the HS-SY-II cell line a SS18-SSX1 translocation; the RD and SW982 cell lines are soft tissue sarcoma cell lines that do not contain an SS18-SSX translocation and were included as controls." (PMID 27391784, 2016).
mesenchymal neoplasm (5 papers, 2023 to 2025). "Synovial sarcoma (SS) is a highly malignant mesenchymal tumour that occurs mainly in adolescents and young adults, genetically defined by SS18 gene fusions including SS18–SSX1, SS18–SSX2, and SS18–SSX4." (PMID 37417899, 2023). "We report a uterine myxoid mesenchymal tumor with a novel SS18::VEZF1 gene fusion." (PMID 40878061, 2025).
salivary gland tumor (5 papers, 2023 to 2025). "Microsecretory adenocarcinoma (MSA) is a newly identified entity in the WHO classification of salivary gland tumors characterized by MEF2C::SS18 fusion." (PMID 40176070, 2025). "Microsecretory adenocarcinoma was identified as a newly discovered salivary gland tumor via molecular studies that showed a low-grade adenocarcinoma with a specific MEF2C:SS18 fusion." (PMID 38929710, 2024). "Currently, MEF2C::SS18 fusion has been reported in microsecretory adenocarcinoma (MSA), a novel subtype of salivary gland adenocarcinoma that tends to be less malignant or appears as an inert salivary gland tumor." (PMID 38907739, 2024).
soft tissue tumors (5 papers, 2022 to 2025). "The SUMOylation cascade represents as targetable regulator of the SS18::SSX fusion oncogene in soft tissue tumors." (PMID 40804185, 2025). "This multi-screen study identifies SUMO2 as a critical regulator of the SS18::SSX fusion oncogene, suggesting a novel vulnerability for these soft tissue tumors." (PMID 40804185, 2025).